CD44 (CD44 molecule (IN blood group))
Diseases named in the same sentence as CD44 in open-access papers (continued):
Sharing a sentence is not in itself a finding about the gene and the disease.
tumor (continued). "However, the expression of CD44 was also found to be negatively associated with tumor invasiveness and Gleason grades, which is mainly related to the switch between CD44s and CD44v on the cancer cells through alternative splicing of CD44 isoforms." (PMID 38783892, 2024). "Accumulating evidence indicates that CD44 is involved in various cancer-associated pathways, and, in recent years, there has been an increasing awareness of the plethora of functions of CD44 in the tumor context." (PMID 39596815, 2024). "Indeed, CD44-positivity in gastric CSCs is associated with enhanced metastatic ability, as well as an ability to differentiate and recapitulate a heterogeneous tumor." (PMID 38612911, 2024). "CD44 antigens, which are themselves glycoproteins, function as receptors of proteoglycans (one subtype of glycan) including hyaluronic acid and chondroitin sulfates, and these interactions are known to be tumor-associated." (PMID 39123480, 2024). "Datasets of 33 cancer types from The Cancer Genome Atlas (TCGA) database were applied to investigate the relationship of CD44 expression with prognosis, tumor mutational burden (TMB), and microsatellite instability (MSI), and determine its potential prognostic value in pan-cancer." (PMID 37117249, 2023). "The observed differences in CD44 impact on OC biology might be caused by many mRNA splice variants of CD44 and their various effects on the tumor characteristics." (PMID 37628927, 2023). "The intensity of CD44 staining was positively associated with the tumor stage." (PMID 37509716, 2023). "Furthermore, various studies showed that increased expression of CD44 or CD44v6 was found in gastrointestinal tumors and was associated with tumor invasion, lymph node metastasis, and patient survival." (PMID 37328876, 2023). "CD44 was reported to be associated with glial dynamics in the tumor microenvironment." (PMID 36776876, 2023). "Besides, MIF-(CD74+CXCR4) and MIF-(CD74+CD44) pathways were widespread and are associated with multiple cell types in the tumor and normal tissues." (PMID 37335089, 2023). "Interestingly, the CD44 gene contains a central region of nine exons that can be alternatively spliced, giving rise to CD44 variant isoforms (CD44v) with additional pro-tumor functions." (PMID 38003753, 2023). "And, CD44+ CRC cells have tumor-initiating ability in immuno-deficient mice." (PMID 37005380, 2023). "Therefore, the understanding of each CD44 variant’s (CD44v) function and distribution in carcinomas is essential for the establishment of CD44-targeting tumor therapy." (PMID 37218897, 2023). "CD44 is a protein whose membrane expression is associated with the most aggressive cells in tumor and may be recognized as an additional prognostic marker for various malignant tumors." (PMID 36835465, 2023). "Notably, in HCC, cytokine IL-6 released by tumor-associated macrophages can enhance the expansion of CD44+ CSCs." (PMID 37835585, 2023). "At 6 days post-tumor cell injection, analysis of the draining medLNs revealed a 1.8-fold increase in the frequency of CD44+CD69+CD8+ T cells, a phenotype associated with early T cell activation, in B16F10-OVA tumor-bearing B6 mice (B16) compared to uninjected B6 mice." (PMID 37426658, 2023). "We hypothesized that disruption of the Merlin-CD44 complex, through loss of Merlin, may unleash putative tumor- or metastasis-promoting functions of CD44." (PMID 37174657, 2023). "Additionally, in LSCC, both ALDH1 and CD44 staining were associated with smaller tumor sizes (T1/T2; p<0.0001)." (PMID 38126564, 2023). "We also suggest that intercellular adhesion molecule 1 (ICAM-1)—and potentially other molecules—may compensate for loss of CD44 in other tumor relevant processes." (PMID 37174657, 2023). "The mechanisms of regulation of these interactions in different tumor cell types and cancer stages are not well understood and may involve specific variants of CD44." (PMID 37958796, 2023).
tumor (continued). "In summary, previous studies showed that high levels of CD44 expression are associated with a number of factors that indicate a poorer prognosis, such as larger tumor size, more aggressive tumor grade, increased lymph node involvement, metastasis, and decreased survival." (PMID 37958796, 2023). "CD44 positivity is associated with lower Gleason’s grades and tumor staging." (PMID 37461792, 2023). "Therefore, each CD44 variant (CD44v) function and distribution in carcinomas should be clarified for the establishment of novel tumor diagnosis and therapy." (PMID 37189717, 2023). "This led us to hypothesize that disruption of the Merlin-CD44 complex, through loss of Merlin, releases putative tumor- or metastasis-promoting functions of CD44." (PMID 37174657, 2023). "Notably, CD44 is the most common cancer stem cell receptor, its overexpression has been implicated in cancer chemoresistance, tumour relapse, and metastasis." (PMID 37099169, 2023). "To address if the reduced self-renewal capacity of MCF7 NELF-E KO cells may be due to a loss of cancer stem cells (CSCs) or tumor-initiating cells (TICs), we performed flow cytometry analysis using CD44 and CD24 surface markers." (PMID 37117180, 2023). "The CD44 gene produces a cell-surface glycoprotein crucial for cell interactions, adhesion, and motility, generating functionally diverse isoforms through complex alternative splicing, associated with tumor metastasis." (PMID 37884554, 2023). "Conversely, CD44 and its variants, including CD44v6, serve as receptors for hyaluronic acid and are implicated in various processes such as cell adhesion, proliferation, differentiation, survival, and apoptosis of tumor cells." (PMID 37491225, 2023). "Additionally, the underlying mechanisms of CD44 in the tumor microenvironment (TME) were analyzed using ESTIMATE and CIBERSORT algorithms and Gene Set Enrichment Analysis (GSEA)." (PMID 37117249, 2023). "Overexpression of endogenous CD6 ligands (i.e., CD166/ALCAM, CD318/CDCP1, and CD44) is associated with tumour events, so the use of CD6-based CARs may broaden the spectrum of treatable tumours." (PMID 38139340, 2023). "This indicates the role of variant isoforms of CD44 in tumor progression." (PMID 37298284, 2023). "Therefore, establishment and characterization of mAbs that recognize each CD44v is thought to be essential for understanding each variant’s function and development of CD44-targeting tumor diagnosis and therapy." (PMID 37218897, 2023). "High levels of CD44/CD133-positive cells are associated with CD204-expressing M2-type tumour-associated macrophages that generally promote tumour development, and a high co-expression of all three markers is associated with a worse overall and disease-free survival." (PMID 37108193, 2023). "Interestingly, CD44 expression has been shown to be significantly associated with tumor aggressiveness in BC." (PMID 37110670, 2023). "CD44, known as P-glycoprotein 1, has been associated with tumor metastasis and invasion." (PMID 37189176, 2023). "CD44 expression in tumor cells is often associated with increased invasiveness in surrounding tissue and different approaches were used to block CD44 resulting in a less invasive phenotype." (PMID 36876041, 2023). "Given that specific CD44 isoforms have previously been associated with tumor promoting properties, future studies might be aimed at elucidating the possible role of individual isoforms with regard to HT in FL." (PMID 35267625, 2022). "Complicating the scenario, CD44 is subjected to multiple splicing events and the relative importance of specific CD44 splice variants for particular tumor phenotypes has seemingly remained controversial, revealing important discrepancies related to tumor types and stages." (PMID 35805061, 2022).
tumor (continued). "A recent study has shown that CD24−/CD44+ CSCs were associated with cell proliferation and tumor progression, whereas ALDH+ CSCs were more associated with metastasis, indicating that these two markers enrich for different CSC populations with diverse phenotypes." (PMID 35053617, 2022). "Also, a significant decrease of tumour-associated memory cytotoxic T cells (CD8+CD44+CD62L+) was observed after nsECT4 treatment." (PMID 36551739, 2022). "It is hypothesized that CD44 affects patient survival by conferring radio- and chemoresistance in the tumours and causing relapse and metastasis." (PMID 35296132, 2022). "Moreover, we observed an increased expression levels of activation marker (CD44) on cytotoxic tumour-associated T cells, in nsECT4-treated compared to untreated tumour-bearing mice." (PMID 36551739, 2022). "In addition, an increase in the proportion of CD44+CD24−/low cells in the tumour was associated with lymphogenous metastasis." (PMID 35563449, 2022). "In-depth global and phosphoproteomic analyses of tumor cells deficient with CD81 or CD44 unveils endocytosis-related pathway alterations, leading to further identification of a quality-keeping role of CD44 and CD81 in EV secretion as well as in EV-associated stemness-promoting function." (PMID 36193887, 2022). "However, CDCA8 overexpression offset the low proliferation rate of tumor cells caused by the knockdown of CD44." (PMID 36358852, 2022). "The results showed that PLGA-PEG nanoparticles accumulated in the TAM-sufficient tumor by 7-fold higher than that in TAM-deficient tumor, indicating that CD44 may be an ideal target for imaging-guided TAM-oriented cancer immunotherapy." (PMID 36419877, 2022). "CD44 is one of the independent prognostic predictors of moderate survival in renal clear cell carcinoma, which may be associated with tumour immunity, but the underlying mechanism remains unclear." (PMID 36316684, 2022). "Hepatic stellate cells had upregulated NNMT expression and altered H3K27 methylation status, which affected the N6-methyladenosine (m6A) of CD44, consequently contributing to the formation of the splice variant CD44v3, which is closely related to tumor metastasis." (PMID 35756670, 2022). "On the other hand, the association between TF and CD44 reported here in EMT phenotypes is also in line with a massive body of literature that has been reviewed, functionally associating CD44 expression to EMT in a variety of tumor cell lines, in different cancer types and in human CTCs." (PMID 35805061, 2022). "Notably, the high CD44 expression in GC is associated with a larger tumor size, a lower grade of differentiation, tumor relapse, lymph node invasion, metastasis and reduced survival." (PMID 35326607, 2022). "Unexpectedly, snail+ZEB1+CD44+ tumour cell density was associated with longer 5-year survival." (PMID 36358805, 2022). "While CD44 remains understudied in exosome biogenesis, a CD44 variant has been reported to be involved in interluminal vesicle loading which may be linked to maintaining tumor-initiating cells and tumor progression." (PMID 36193887, 2022). "The ligation between osteopontin and different CD44 variants (i.e., CD44v6 or CD44v9) was reported to facilitate tumor migration and metastasis, and EMT may play a role in this relationship." (PMID 36499654, 2022). "CDP0857 treatment significantly reduced the tumor size and volume of D-K-Ras MT cells harboring these mutations, and tumors excised from xenograft mice showed a significantly reduced expression of CD44, CD133 and EpCAM and of active forms of factors in the Wnt/β-catenin and Ras/ERK pathways." (PMID 35453609, 2022). "Additionally, CD44 expression was associated with BCa tumor aggressiveness, and it was related to the prediction of the radiation response of BCa cells." (PMID 35884419, 2022). "Moreover, CD44 is highly associated with tumorigenicity, invasiveness, and lymphatic metastasis of tumor cells." (PMID 35669102, 2022).
tumor (continued). "Interestingly, the molecular weight of HA, which can vary between dozens (≈5 KDa) and thousands of units (2,000 KDa), affects the binding of HA to CD44 and consequently to the effects that it causes in tumor cells." (PMID 35785191, 2022). "CD44 is majorly associated with tumor incursion, evolution, and metastasis." (PMID 36354475, 2022). "Furthermore, SPP1 also binds to CD44, causing cell signaling that mediates tumor progression and metastasis." (PMID 36424413, 2022). "However, in the time-independent study, a significant decrease of tumour-associated memory Tc cells (CD44+CD62L+CD8+) was observed, in nsECT4-treated compared to μsECT and untreated tumour-bearing mice." (PMID 36551739, 2022). "Indeed, FACS analysis demonstrated decreased naïve T cell (CD62L+CD44-) and increased effector-memory T cell (CD62L-CD44+) within tumor-associated CD8+ T cells in BAY-I treated withdrawal cohort as compared to vehicle cohort." (PMID 35013322, 2022). "However, the expression levels of CD44 were increased on tumour-associated TEM and Tregs in nsECT2-treated mice." (PMID 36551739, 2022). "Those surface markers, together with CD44, are associated with immune cell function, such as resistance or susceptibility to NK cell and T cell-mediated recognition and lysis, as well as differentiation stage of tumor cells." (PMID 35538218, 2022). "Interestingly, the CD44v6 variant is one of the CD44 isoforms that more frequently correlates with tumor progression in other malignancies." (PMID 35785191, 2022). "We found that Lef1 deletion in Apc-deficient tumor cells was associated with increased nuclear accumulation of β-catenin and up-regulation of its downstream targets Myc and Cd44, which have been considered as key mediators of intestinal tumorigenesis in the Apc-deficient cells." (PMID 34788095, 2021). "Also, the CD44 variant isoform, CD44v6, acts as a co‐receptor for the receptor tyrosine kinase, c‐Met, and promotes tumor cell invasion." (PMID 33543833, 2021). "Besides, the mesenchymal-like CSCs, strongly implicated in tumor invasion and resistance to therapy, are characterized by the CD44+ phenotype." (PMID 33436039, 2021). "We previously reported that GBMs expressing high CD44 in the tumor periphery show a highly invasive phenotype on MRI and are associated with early tumor progression and worse prognosis compared with GBMs expressing low CD44, which represent a less invasive and highly proliferative phenotype on MRI." (PMID 33543833, 2021). "Tumour-related inflammation has been studied in different cancers, targeting also the associations with cancer stemness, particularly in relation to the levels of CD44, known as a cancer stem cell marker." (PMID 34884696, 2021). "Changes in CD44 expression levels are commonly associated with tumor invasion and metastasis." (PMID 33445605, 2021). "Additionally, a statistically significant association was detected between CD44 positive expression and left-sided tumor in previous studies." (PMID 34837915, 2021). "Indeed, intestinal knockouts of CD44 cause a phenotype similar to the Src KO or Yap/Taz dKO, featuring increased crypt apoptosis and prevention of ApcMin tumour formation." (PMID 33950519, 2021). "CD44 variant isoform exon 9 (CD44v9) was reported to be upregulated in several tumours, and it is thought to be involved in chemo‐resistance and the recurrence of tumours." (PMID 33210459, 2021). "As a matter of fact, CD44 has been shown to be overexpressed in various types of cancers, and a subfamily of CD44 splice variants encompassing the variant domain 6 (CD44v6) has been implicated in the metastatic potential of tumours." (PMID 33504020, 2021). "The positive expression of CD44 and its variants may play important roles in the tumor infiltration, metastasis and poor prognosis of CRC." (PMID 34214117, 2021).
tumor (continued). "Moreover, both CD133- and CD44-positive cells are more resistant to anticancer therapies and are closely associated with tumor progression and poor prognosis." (PMID 33819194, 2021). "Third, although the macrophage-mediated SPP1/CD44 signaling has been implicated in regulating the evolution of MES-like tumor cells in this study, the precise mechanisms driving the transition from OPC/NPC-like to MES-like cells have not been investigated, which need to be addressed in the future." (PMID 34805184, 2021). "Tumor-specific splice variants of CD44 may be worth testing for their potential ease of use in tissue and liquid biopsies (Eibl, unpublished)." (PMID 34771592, 2021). "To answer these questions and clarify the role for CD44 in VEGF‐promoted angiogenesis, we investigated the inhibitory effects of VEGF on CD44 expression and tumor invasion using cultured GSC lines because GSCs in the tumor border are thought to be causal cells expressing activated CD44." (PMID 33543833, 2021). "Although it is known that the canine CD44 gene encodes 20 exons, including 10 variant exons, as observed with the human CD44 gene, the expression pattern and role of CD44 isoforms in canine tumours remain unclear." (PMID 33210459, 2021). "Likewise, the detection of a tumor initiating cell (TIC) phenotype (evaluated with the expression of aldehyde dehydrogenase, CD133, and CD44) was associated with tumor recurrence and decreased DFS." (PMID 33924143, 2021). "Indeed, upregulation of the CD44 variant v6 caused by SFN resulted in the inhibition of tumor cell invasion." (PMID 32759798, 2020). "The presence of CD44-associated circRNAs in tumor cells may provide new clues regarding the tumor cell-platelet interaction." (PMID 32943996, 2020). "Many effects of HA in tumor biology depend on HA size and concentration, as well as presented form, and they rely on the interaction with its main cellular receptors CD44 (and tumor specific splice variants thereof) and HA-mediated motility receptor (RHAMM) of the cancer cells." (PMID 33008082, 2020). "Additionally, overexpression of specific CD44 RNA splicing variants, namely CD44v8-10 in BC, has been shown to be closely associated with tumor progression, aggressiveness, and metastasis." (PMID 31963556, 2020). "Interestingly, they also demonstrated that de novo production of LOX by mesenchymal stromal cells (MSCs) associated to tumor is able to transduce the same signal along the CD44–LOX–Twist axis." (PMID 32793478, 2020). "CD44 is widely expressed in most vertebrate cells, whereas the expression of CD44v6 is restricted to only a few tissues and has been considered to be associated with tumor progression and metastasis." (PMID 31947887, 2020). "Moreover, the palmitoylations on CD44 control the association/dissociation switching of CD44 and Radixin, a process, that has been identified in tumor cell migration and proliferation." (PMID 32271757, 2020). "Thus, our results suggest that CD44 signaling within tumor cells impacts the phenotype of infiltrating tumor-associated macrophages (TAMs), potentially by altering pro-inflammatory mediators." (PMID 32455980, 2020). "Subgroup analyses showed that the association between tumor CD44 expression and poor OS may be different according to the WHO stages of the tumor." (PMID 32232385, 2020). "Moreover, the stiffness gradient in the TME in breast cancer is associated with specific CSC phenotypes, CSC CD24−/CD44+ localized in the tumor edges is quiescent, and CSC ALDH+ (more stem) is found in the tumor core." (PMID 33177991, 2020). "Tumor cells expressing high levels of CD44 have been associated with gemcitabine resistance." (PMID 32308769, 2020). "Interestingly, the combination of PTX with TQ significantly abolished the tumor-associated stem cell clone (CD44+/CD24-) by 32.3 ± 0.08%." (PMID 31968657, 2020). "Variations of the expression of CD44 isoforms have been implicated in tumor development." (PMID 32736579, 2020).